YAP1 (Yes1 associated transcriptional regulator)
Diseases named in the same sentence as YAP1 in open-access papers (continued):
Sharing a sentence is not in itself a finding about the gene and the disease.
breast cancer (continued). "In the context of deubiquitination studies, a recent investigation has revealed that USP9X specifically targets YAP1 for deubiquitination and stabilization, thereby facilitating breast cancer cell survival and progression." (PMID 40034124, 2025). "While several DUBs, such as USP10 and USP9X, have been reported to affect YAP1 ubiquitination in HCCs and breast cancers respectively, the deubiquitinating enzyme responsible for YAP1 regulation in CRC has remained unidentified." (PMID 39968498, 2025). "The decreased m6A impedes YTHDF2-mediated degradation of YAP1 to enhance the tumor cell stemness in breast cancer." (PMID 40822927, 2025). "YAP1 is a key protein in the Hippo pathway that supports cancer growth and survival, particularly in aggressive breast cancers like triple-negative tumors." (PMID 40731926, 2025). "E2 via ER-α modulates YAP1 expression by inducing hypomethylation of its promoter region through the downregulation of DNMT3B in ER-α-positive breast cancer cells." (PMID 41294885, 2025). "In breast cancer, tumor cells maintain a stem-like phenotype by activating YAP1 signaling, and YAP1 also acts as a mechanical sensor in hepatocellular carcinoma." (PMID 40822927, 2025). "The downstream Hippo pathway effector yes-associated protein 1 (YAP1) and its paralog, TAZ, have been identified as STAT3 interacting proteins in breast cancer." (PMID 40507264, 2025). "Conversely, the inhibition of either ROR1 or YAP1 was sufficient to re-sensitize the HER2+ breast cancer cell line HCC1954 to T-DM1." (PMID 40869147, 2025). "Previous research showed that YAP1 binds to KLF Transcription Factor 5 (KLF5) dependent on the two WW domains of YAP1 and enhances the growth of breast cancer cells." (PMID 40124511, 2025). "In summary, our results demonstrate that overexpression of LRRC56 promotes breast cancer progression via upregulating IFT88/YAP1-RhoA/ROCKs pathway, reprogramming extracellular matrix, and enhancing epithelial-mesenchymal transition." (PMID 40388100, 2025). "For example, research conducted in breast cancer shows that AURKA-mediated nuclear phosphorylation of YAP1 at this residue increases its stability and transcriptional activity." (PMID 38467828, 2024). "Another study showed that the knockdown of Linc-OIP5 suppressed the angiogenesis of the HUVECs through YAP1/Notch/NRP1 signalling in breast cancer." (PMID 39219375, 2024). "Wang and colleagues illustrated that AURKA stabilises YAP1 and enhances its protein levels in breast cancer models." (PMID 38467828, 2024). "YAP1 activation is associated with this resistance, prompting an investigation into AURKA’s role in mediating YAP1 phosphorylation at Ser397, as observed in breast cancer." (PMID 38467828, 2024). "This is in stark contrast to ER+ breast cancers, in which YAP1 impairs ER-dependent growth, underscoring the regulatory specificity of YAP1 in poorly differentiated breast cancers." (PMID 39563370, 2024). "Analysis of YTHDF2 cross-linking and immunoprecipitation datasets across multiple breast cancer cell lines showed that the binding signals of YTHDF2 covered the m6A-specific peak around the stop codon of YAP1." (PMID 39563370, 2024). "To determine if this was true, we treated breast cancer cells with actinomycin D (Act.D) and examined the decay rate of YAP1 mRNA." (PMID 39563370, 2024). "In a study on breast cancer, USP9x was found to promote chemoresistance through the stabilization of the transcriptional regulator YAP1." (PMID 39075050, 2024). "Unexpectedly, through boosting the abundance of CD8 + T cells, the overexpression of YAP1 was found to inhibit the growth of melanoma cells, squamous cell carcinoma cells, and breast cancer cells." (PMID 37752152, 2023). "Cytoplasmic yes-associated protein 1 (YAP1) promotes autophagic death in breast cancer cells, and NEDD4L mediates ubiquitination and downregulation of YAP1." (PMID 38027016, 2023).
breast cancer (continued). "cAMP response element-binding protein (CREB) transcription factor is a positive regulator of YAP1 transcription and an integrin alpha 5 (ITGA5)/FAK/CREB signaling axis was described to enhance YAP1 transcription in breast cancer." (PMID 36936987, 2023). "Recently, several studies regarding the Hippo signaling pathway and ERα regulation suggested the inhibitory role of YAP1 on ER+ breast cancer growth." (PMID 37894401, 2023). "In a more recent study, RUNX3 expression in YAP1-expressing normal mammary epithelial cells, and breast cancer cells, suppressed YAP1-mediated proliferation, migratory capacity and EMT." (PMID 36831308, 2023). "There is evidence that YAP-1 is overexpressed in different types of cancer, including cancers of the breast, pancreatic, colon, lung, ovary, and central nervous system." (PMID 37476371, 2023). "This favorable prognostic impact of YAP1 expression was also seen in the public datasets analyses, which showed significant superior survival in high-YAP1 group of IHC-defined ER+ breast cancer." (PMID 37894401, 2023). "As we observed in our previous study, YAP1 expression increased along with tumor stiffness in HR+HER2− breast cancer." (PMID 37894401, 2023). "YAP1 physically interrupts the ERα/TEAD interaction by competing with ERα in ER+ breast cancer cells." (PMID 37894401, 2023). "In a previous study, we showed that YAP1 nuclear expression was increased along with tumor stiffness measured by shear-wave elastography in HR+HER2− breast cancer." (PMID 37894401, 2023). "Collectively, YAP1 acts differently in ER+ breast cancer cells by inhibiting the downstream signaling pathway of the ESR1 gene, which is crucial for ER+ tumor growth." (PMID 37894401, 2023). "In breast cancer, miR-556-5p inhibits cell proliferation and invasion by targeting YAP1, which is a transcription factor that regulates the expression of genes involved in cell cycle progression and apoptosis." (PMID 37670963, 2023). "Lastly, the different role of YAP1 as a mechanotransducer in HR+HER2− breast cancer should be further elucidated in the context of clinical implication." (PMID 37894401, 2023). "The natural component physalin A also reduces YAP1 levels in breast cancer and impacts the proportion of BCSCs." (PMID 37492224, 2023). "This study explores the relationship between YAP1 expression and the risk score from the Oncotype Dx test in patients with hormone-receptor-positive, HER2-negative (HR+HER2−) breast cancer." (PMID 37894401, 2023). "In support of our findings, a tumor-suppressive role of YAP1 overexpression has been observed in cervical cancer HeLa cells, breast cancer MCF7 cells, glioblastoma D645 cells, and head and neck cancer cells." (PMID 35930163, 2022). "In this study, we analyzed the correlation between nuclear YAP1 expression and tumor stiffness in breast cancer." (PMID 36291755, 2022). "Although Li and colleagues conducted limited functional studies, overexpression of ESR1-e6>YAP1 in ER+ breast cancer cells conferred estradiol-independent growth in their study." (PMID 36686845, 2022). "This can provide new approaches to better understand the relation between YAP1 and IL‐18 in breast cancer progression by performing in vitro and in vivo studies." (PMID 34196131, 2022). "In this report, we analyze the publicly available breast cancer gene expression datasets (TCGA and METABRIC) to evaluate the association of these signature genes individually and in combination with YAP1." (PMID 35407556, 2022). "In another study, YAP1 was found to regulate ROR1 expression, and Wnt5A/ROR1–YAP1/TAZ feedback loop was associated with cancer stem cell phenotype, tumor progression, metastasis, and, ultimately, drug resistance of breast cancer." (PMID 35053353, 2022). "Upregulation of YAP1 expression has been detected in breast cancer, melanoma, and hepatocellular carcinoma, suggesting that YAP1 is essential for tumor initiation." (PMID 36008392, 2022).
breast cancer (continued). "Taken together, these data demonstrated that YAP1 is necessary and sufficient for invadopodia formation in breast cancer cell lines." (PMID 35773411, 2022). "Nuclear localization of YAP1 showed correlation with tumor stiffness in hormone-receptor positive (HR+) breast cancer." (PMID 36291755, 2022). "With YAP1 established as an oncogene in breast cancer, multiple studies have been conducted to assess the mechanistic role of YAP1 target genes in promoting oncogenic phenotypes in mammary epithelial cell lines and breast cancer cell lines." (PMID 35407556, 2022). "An in vitro study showed that YAP1 was activated when breast cancer progressed from in situ carcinoma to invasive carcinoma." (PMID 36291755, 2022). "In this regard, it is worth noting that both CLP36 and YAP1 have been found to promote the progression of glioma, breast cancer, and CML 31, 45-48." (PMID 35836803, 2022). "Guo et al4 described that YAP1 suppresses cell apoptosis and encourages cell proliferation in breast cancer through the phosphatase and tensin homolog deleted 10–AKT signaling pathway." (PMID 34196131, 2022). "In the present study, we report that YAP1 induces invadopodia formation and promotes tumor metastasis in breast cancer cells." (PMID 35773411, 2022). "Transwell migration, invasion, and wound-healing assays revealed that YAP1 regulates breast cancer cell migration and invasion in vitro, consistent with our previous results." (PMID 35773411, 2022). "Controversies have been reported regarding the clinical significance of YAP1 expression in breast cancer." (PMID 36291755, 2022). "E2 exerts pro-growth and anti-apoptotic effects by upregulating the expression of YAP1 in breast cancer cells." (PMID 36220823, 2022). "Because HJURP and YAP1 are both highly expressed in basal-like breast cancer, YAP1 as a transcriptional factor plays an important role in TNBC." (PMID 35459269, 2022). "Patients having a higher expression of IL‐18 possess a better prognosis and higher YAP1 expression with lower IL18 drives to poor clinical results in breast cancer." (PMID 34196131, 2022). "In conclusion, we verified a positive correlation between YAP1 expression and tumor stiffness in breast cancer." (PMID 36291755, 2022). "In breast cancer, YAP1 overexpression in tumor promotion and patient prognosis have been controversial." (PMID 36291755, 2022). "We confirmed the activation of YAP1 in breast cancer using human breast cancer tissue and immunohistochemistry." (PMID 36291755, 2022). "For example, THBS1 (thrombospondin 1) activates focal adhesion kinase when transcriptionally activated by YAP1, which regulates breast cancer progression and metastasis, promoting tumor aggressiveness." (PMID 35407556, 2022). "In conclusion, our findings reveal a potential mechanism via which YAP1 induces invadopodia formation and promotes tumor cell metastasis in breast cancer." (PMID 35773411, 2022). "Overexpression of YAP1 correlates with poor prognosis in human cancers, including ovarian cancer, non-small cell lung cancer, esophageal cancer, and breast cancer." (PMID 36291755, 2022). "In this study, we demonstrated that YAP1, the key component of Hippo signaling, induces invadopodia formation in breast cancer cells." (PMID 35773411, 2022). "circYAP interfered with YAP1 translation initiation machinery assembly, thereby repressing proliferation, colony formation and migration in breast cancer and liver cancer cells." (PMID 35673576, 2022). "Despite these limitations, the results demonstrated that nuclear YAP1 expression was a clinical prognostic factor in breast cancer, especially TNBC." (PMID 33718163, 2021). "The aim of this study was to correlation between the level of nuclear YAP1 expression and the clinical characteristics and survival rates of patients with breast cancer." (PMID 33718163, 2021).
breast cancer (continued). "Our findings suggest that nuclear YAP1 expression is a biomarker of adverse prognosis and a potential therapeutic target in patients with breast cancer, especially in TNBC." (PMID 33718163, 2021). "Here, we report that in breast cancer and cholangiocarcinoma, the YAP1 pathway and mTORC1 pathway are coactivated." (PMID 34462427, 2021). "After being absorbed by cancer cells, the miR-92 targets large tumor suppressor kinase 2 (LATS2) that interacts with Yes-associated protein 1 (YAP1) and regulates nuclear translocation of YAP1 in breast cancer cells." (PMID 34852849, 2021). "Activated YAP1 is generally considered to be an oncogene in diverse solid cancers, but there is still controversy regarding the role of YAP1 of breast cancer." (PMID 33970925, 2021). "Using a comprehensive in-silico data analysis on the breast cancer cohort from TCGA, we showed the enrichment of high-level YAP1 expression in samples with the highest stromal score." (PMID 34680267, 2021). "Taken together, these results are consistent with the notion that pharmacological suppression of YAP1 phenocopies the effect of RASSF1A expression in ERα expressing breast cancer cells." (PMID 34831091, 2021). "One study reported the no significant role of YAP1, and the others showed that YAP1 was the favorable predictor, and functioned as a tumor suppressor in breast cancer." (PMID 33970925, 2021). "Conversely, there were also studies that described YAP1 as a poor prognostic factor mediating tumor development and progression of breast cancer." (PMID 33970925, 2021). "Our data indicated that YAP1 and phosphorylated 70S6K (Thr389) exhibited high positive rates compared with paired adjacent normal tissues in breast cancer, cholangiocarcinoma and colon cancer." (PMID 34462427, 2021). "YAP1 can enhance CSC stemness in several types of human cancers, and aberrant YAP1 activation is associated with a low level of TNBC differentiation and poor survival of breast cancer patients." (PMID 34318746, 2021). "Yes-associated protein 1 (YAP1) is a key effector molecule regulated by the Hippo pathway and described as a poor prognostic factor in breast cancer." (PMID 33970925, 2021). "On the other hand, YAP1 has been reported to function as a tumour suppressor in breast cancer and haematological malignancies by promoting apoptosis in these contexts." (PMID 33611811, 2021). "Although YAP1 is commonly considered a proto‐oncogene, recent studies have demonstrated its tumour‐suppressive role in haematological cancer, breast cancer and even lung SCC cancer." (PMID 33611811, 2021). "In order to further evaluate, the association between identified cytokines with EMT and YAP1, we analyzed expression of these cytokines in samples with high and low expression of YAP1 from TCGA breast cancer cohort." (PMID 34680267, 2021). "The Hippo signaling pathway has become increasingly important in human cancer; the key regulator YAP1 is upregulated in breast cancer, colorectal cancer, and liver cancer; and YAP1 promotes proliferation and inhibits apoptosis." (PMID 34660259, 2021). "Our data therefore provide support for the development of drugs that target YAP1 as a therapeutic opportunity for the treatment of ERα-driven breast cancer." (PMID 34831091, 2021). "In conclusion, we suggested that nuclear YAP1 expression is a clinical prognostic factor for breast cancer." (PMID 33718163, 2021).
breast cancer (continued). "For multiple cancer types, such as lung, esophageal, gastric, pancreatic, and breast cancer, we detected a significant correlation between prognosis and YAP1 expression." (PMID 34150844, 2021). "MicroRNA-135b binds to LATS2, a member of the hippo-YAP1 axis, inducing cell proliferation, migration, and invasion in breast cancer." (PMID 34082774, 2021). "To better understand the potential association of YAP1 with classical stemness and EMT markers, we comprehensively analyzed the gene and protein expression levels of YAP1 across 1084 breast cancers from the TCGA cohorts." (PMID 34680267, 2021). "Here, we investigated the impact of different levels of nuclear YAP1 expression on the clinical characteristics and survival outcome in patients with breast cancer." (PMID 33718163, 2021). "Our data indicated that YAP1 and phosphorylated 70S6K (Thr389) exhibit high positive correlations compared with paired adjacent normal tissues in breast cancer, cholangiocarcinoma and colon cancer." (PMID 34462427, 2021). "Amplifying YAP1 leads to the acquisition of oncogenic cell features, including rapid proliferation, migration and invasion in breast cancer." (PMID 33336871, 2021). "An additional example is circ_0005273 (gene of origin: PTK2), which regulates the Hippo/YAP (YAP1) pathway through sponging miR-200a-3p, in order to promote breast cancer tumorigenesis." (PMID 34205978, 2021). "Knockdown of YAP1 in ERα+ MCF7 breast cancer cells led to reduced expression of ERα and FOXM1, cell cycle arrest, and senescence and inhibition of AKT1 and increased activity of FOXO3A." (PMID 32967092, 2020). "This cross-talk between HER family and Hippo-YAP1 networks holds numerous implications for tackling the resistance to trastuzumab in breast-cancer cells." (PMID 32365528, 2020). "Taken together, these results therefore suggested that YAP1/TEAD1-2 can affect tumor growth in HER2-positive breast cancer, likely by promoting cell proliferation." (PMID 32365528, 2020). "In breast cancer, YAP1 can directly interact with ZEB1, (a crucial stimulator of EMT processes) and thereby increases metastatic risk." (PMID 32678516, 2020). "On the contrary, abundant literature suggested that YAP1 is a tumor suppressor gene and nuclear expression is reduced in different cancers, such as breast cancer, head and neck cancers, hematological cancers, and CRC." (PMID 33240680, 2020). "The GSEA indicated that YAP1 signaling-related genes were enriched in breast cancer cell lines and tumors which expressed low ERK1 levels." (PMID 31848326, 2019). "In conclusion, our study demonstrated that ERK1 and ERK2 showed distinct expression pattern, prognostic value and function in regulation of YAP1 signaling in breast cancer." (PMID 31848326, 2019). "In current study, we focused on the specific roles of ERK1 and ERK2 on regulation of YAP1 in breast cancer." (PMID 31848326, 2019). "The heatmap analysis suggested that low expression of ERK1 enriched high expression of YAP1 and its target genes in breast cancer cells." (PMID 31848326, 2019). "The downregulation of YAP1 by ERK2 silencing was further observed in basal breast cancer cells (MDA-MB-231 and HS578T)." (PMID 31848326, 2019). "Western blot analysis was carried out to analyze the relationship between miR-591 expression and YAP1 expression in breast cancer." (PMID 31049030, 2019). "The results demonstrated that ERK1 inhibited the growth of breast cancer cells and tumors via downregulation of YAP1." (PMID 31848326, 2019). "The in vitro and in vivo assays suggested that ERK1 inhibited breast cancer progression via downregulation of YAP1." (PMID 31848326, 2019).